TREM1 (triggering receptor expressed on myeloid cells 1)
Diseases named in the same sentence as TREM1 in open-access papers (continued):
Sharing a sentence is not in itself a finding about the gene and the disease.
Sepsis (continued). "The clinical observation suggested the potential of using soluble TREM-1 in blood as a prognostic indicator for S. progenie-induced sepsis." (PMID 37456011, 2023). "A soluble form of TREM-1 is also increased in the serum of septic mice, while inhibition of TREM-1 protects mice from endotoxemia and cecal ligation and puncture-induced sepsis." (PMID 37168858, 2023). "TREM-1, a receptor expressed in myeloid cells, including macrophages, is upregulated in inflammatory diseases such as sepsis and its upregulation dysregulates the innate immune system, resulting in tissue injuries and poor prognosis." (PMID 37168858, 2023). "The peptide LR12 is composed of 12 amino acids with anti-inflammatory effects in the LP17 sequence, which also acts as decoy receptors of TREM-1 and protects against sepsis-induced cardiovascular dysfunction and multiple organ failure." (PMID 37168858, 2023). "TREM-1, a mediator of inflammation and prognostic biomarker in sepsis, was elevated in patients who developed severe disease, though did not achieve statistical significance after adjustment for multiple comparisons." (PMID 37026003, 2023). "In macrophages of mice with E. coli-induced sepsis, triggering receptors expressed on myeloid cells-1 (TREM-1), PI3K, AKT, and mTOR are activated in a cascade." (PMID 38274792, 2023). "Our analysis showed enhanced levels of SYT13, IL1F10, and S100A10 cytokines in early sepsis patients, while TREM1 levels in trauma patients increased gradually over time." (PMID 38283341, 2023). "Studies using TREM-1 knockout mice have demonstrated that this receptor plays a critical role in the progression of sepsis." (PMID 35784361, 2022). "N1 is another novel peptide that effectively inhibits TREM-1 induced inflammation, but requires additional studies looking at its efficacy in a polymicrobial model of sepsis to better evaluate it as a treatment modality." (PMID 35784361, 2022). "The protein expression of TREM-1 was higher in the LPS-induced sepsis in vitro model than in the control (p < 0.01)." (PMID 36110326, 2022). "Triggering receptor expressed on myeloid cells 1 (TREM-1) has the ability to promote NET release from neutrophils during sepsis, which can stimulate ECs and damage vascular reactivity, and TREM-1 inhibition suppressed these harmful effects." (PMID 36059483, 2022). "The involvement of TREM-1 in sepsis induced vascular dysfunction was further proven using endoTREM-1-/- mice." (PMID 35784361, 2022). "Increased TREM1 levels have been found in Alzheimer’s disease, Parkinson’s disease and sepsis, but to our knowledge this is the first time an increase in plasma TREM1 levels is found in ageing." (PMID 36189218, 2022). "Many of the following TREM-1 inhibitory peptides developed as a treatment modality for sepsis are based on amino acid (aa) sequences found in sTREM-1, further demonstrating that sTREM-1 is effective as an anti-inflammatory mediator." (PMID 35784361, 2022). "This amplification of the inflammatory response by TREM-1 has now been considered as a critical contributor to the dysregulated immune responses in sepsis." (PMID 35784361, 2022). "Studies had found that two other forms of TREM-1, namely, the mRNA transcription level and the protein expression level of TREM-1 on the cell surface had a certain clinical value in the identification and/or prognosis of sepsis." (PMID 35935355, 2022). "TREM-1 activation on endothelial cells was recently discovered to play a role in the progression of sepsis." (PMID 36246143, 2022). "The inhibition of TREM-1 remains a promising target for development of therapeutic agents to treat sepsis." (PMID 35784361, 2022). "Both eCIRP and TREM-1 are upregulated during sepsis, leading to endothelial cell activation and dysfunction, but their interaction has not been studied in this cell type, specifically as a contributory factor to SA-AKI." (PMID 36246143, 2022).
Sepsis (continued). "TREM-1 activation has long been studied as a player in the dysregulated immune response in sepsis and, in its soluble form, is also predictive of sepsis severity, mortality, and development of sepsis-induced AKI (SA-AKI)." (PMID 36246143, 2022). "GF9 and SLC-TREM-1 demonstrate that targeting the interaction of TREM-1 with DAP12 is a viable TREM-1 inhibitory strategy with potential for drug development in sepsis." (PMID 35784361, 2022). "TREM-1 modulation has proven a promising strategy for the development of therapeutic agents to treat sepsis." (PMID 35784361, 2022). "The identification of TREM-1’s endogenous ligands is crucial for studying the role of TREM-1 in the pathogenesis of sepsis." (PMID 35784361, 2022). "Future work should focus on further characterizing the effects of CIRP/TREM-1 pathway on renal endothelial cell activation using models for sepsis and exploring M3 as a treatment for SA-AKI." (PMID 36246143, 2022). "The sTREM-1 molecule is the cleaved extracellular domain of TREM-1 that was found to be increased in the blood during sepsis." (PMID 35784361, 2022). "As a result, a considerable effort has been made towards identifying endogenous ligands of TREM-1 and developing TREM-1 inhibitory peptides to attenuate the exacerbated inflammatory response in sepsis." (PMID 35784361, 2022). "This review aims to give an overview of the role of TREM-1 and its endogenous ligands in sepsis, and the development of novel inhibitors of this pathway and their efficacy for the treatment of sepsis." (PMID 35784361, 2022). "Understanding the structure and signaling pathway of TREM-1 remains an important focus of research to better elucidate its role in sepsis and to develop novel therapeutic targets." (PMID 35784361, 2022). "eCIRP was recently explored as an endogenous ligand of TREM-1, capable of inducing a sepsis-like inflammatory response and propagating an inflammatory cascade in murine models of polymicrobial sepsis." (PMID 36246143, 2022). "This amplification of the inflammatory response by TREM-1 has gained interest as a critical contributor to the dysregulated immune response in sepsis." (PMID 35784361, 2022). "Modulation of TREM-1 activation with many of these inhibitors has been demonstrated as an effective approach for attenuating sepsis severity." (PMID 35784361, 2022). "TREM-1 has an essential role in systemic inflammatory conditions, including cardiovascular disorders, obesity, sepsis, and pneumonia." (PMID 35329310, 2022). "CD64 and human triggering receptor expressed on myeloid cells-1 (TREM-1) reflecting the function of neutrophils can serve as potential biomarkers for sepsis." (PMID 35619710, 2022). "Mice genetically deficient in TREM-1 are another valuable tool to help uncover the potential benefits of modulating TREM-1 for the treatment of sepsis." (PMID 35784361, 2022). "Sepsis induced the activation of granulocytes and monocytes/macrophages, which highly express TREM-1." (PMID 33390769, 2021). "Compared to sepsis and bacterial pneumonia, studies evaluating the role of TREM1 in aspergillosis are relatively limited." (PMID 33525982, 2021). "Blockade of TREM-1 with TREM-1/Fc fusion protein, TREM-1 peptide, or TREM-1 siRNA rescues mice from sepsis and delays tumor progression in xenographs." (PMID 35223446, 2021). "It has been reported that TREM1 is upregulated in neutrophils both from sepsis patients and LPS-induced septic shock mice." (PMID 33954188, 2021). "We found that iPSC-CM reduced nuclear factor (NF)-κB activity and neutrophil chemotaxis by reducing the expression of TREM-1 and p38 mitogen-activated protein kinase signaling in sepsis-induced ALI." (PMID 34074039, 2021). "Patients with sepsis display increased concentrations of sTREM-1 (soluble Triggering Receptor Expressed on Myeloid cells 1), and a phase II clinical trial focusing on TREM-1 modulation is ongoing." (PMID 34195785, 2021).
Sepsis (continued). "First, studies in mice show a favourable effect of transgenic or pharmacological TREM-1 modulation on sepsis survival." (PMID 34195785, 2021). "One pathway extensively investigated in sepsis and other acute and chronic inflammatory conditions is Triggering Receptor Expressed on Myeloid cells 1 (TREM-1)." (PMID 34195785, 2021). "Increased soluble triggering receptor expressed on myeloid cells 1 (sTREM-1) levels have been reported in patients with sepsis." (PMID 34829326, 2021). "In the present study of a neonatal murine model of polymicrobial abdominal sepsis, we demonstrated that sepsis treatment with the eCIRP-derived TREM-1 inhibitor M3 reduced systemic, pulmonary, and cardiac inflammation." (PMID 33276725, 2020). "We recently showed TREM-1 is a novel endogenous ligand of eCIRP and this interaction promotes an inflammatory response in sepsis." (PMID 32984356, 2020). "We focused on elucidating the direct anti-inflammatory effect of M3 by targeting the interaction between eCIRP and TREM-1 in immune cells and cardiomyocytes in sepsis." (PMID 33276725, 2020). "To evaluate the impact of the eCIRP/TREM-1 interaction in neonatal sepsis, we treated pups with the M3 peptide or normal saline vehicle after sepsis induction with CS." (PMID 33276725, 2020). "In sepsis, the upregulation of TREM-1 by bacterial lipopolysaccharide (LPS) magnifies the inflammatory reaction, leading to the improvement of sensitivity of diagnosing inflammation." (PMID 32508526, 2020). "Although TREM-1 are demonstrated to amplify inflammation in sepsis, soluble TREM-1 has been taken as an antiinflammatory mediator in sepsis." (PMID 32009956, 2019). "Considering the need for novel diagnostic approaches in the treatment of sepsis, other studies discussed the role of soluble TREM-1 as a potential biomarker in sepsis." (PMID 30832396, 2019). "During various models of sepsis, we observed that the TREM-1 inhibition, in addition to reducing inflammation and improving survival, prevented from hemodynamic instability." (PMID 31632399, 2019). "Triggering receptor expressed on myeloid cells 1 (TREM-1) amplifies inflammatory responses and is upregulated during sepsis and pulmonary infection." (PMID 29844416, 2018). "Considering the contribution of interaction between platelets and immune cells to the development of sepsis, further identification of the ligands for TREM-1 activation in platelets was performed." (PMID 29619033, 2018). "In fact, TREM-1 and its interaction with TLRs were consistently involved in acute infective diseases, such as pneumonia, septicemia, and gingivitis." (PMID 30205488, 2018). "Moderate expression of TREM-1 during sepsis seems to improve survival in mice, but high expression increases mortality." (PMID 30018308, 2018). "It is well-known that membrane-bound TREM-1 plays an important role in implications of immune response during sepsis, and there is also an increase of sTREM-1 in blood during sepsis." (PMID 30205488, 2018). "In contrast to bacterial pneumonia and sepsis, information regarding the role of TREM-1 in pulmonary TB is relatively scarce." (PMID 29844416, 2018). "The natural ligand for TREM-1 is present on platelets, which is indispensable for regulating inflammatory processes such as sepsis." (PMID 28824642, 2017). "Triggering receptor expressed on myeloid cells-1 (TREM-1) is a potent amplifier of pro-inflammatory innate immune reactions, and it is an essential mediator of death in sepsis." (PMID 28824642, 2017). "Previous research identified a natural ligand of TREM-1 distributed on platelets that contributed to the development of sepsis." (PMID 28824642, 2017). "Apart from inducing a marked increase in TREM-1 expression, sepsis also induces a soluble form of TREM-1 (sTREM-1), detectable in biological fluids." (PMID 27116911, 2016).
Sepsis (continued). "Commonly expressed genes were significantly associated with several canonical pathways known to be involved in sepsis pathogenesis, including over expression of IL-1 signaling, IL-10 signaling and TREM-1 signaling." (PMID 26871709, 2016). "Previous studies have demonstrated that soluble TREM-1 levels are up-regulated in plasma of patients with sepsis, pneumonia and melioidosis." (PMID 27253382, 2016). "Data showed that, individually, CD64 was more reliable than TREM-1 expressed on PMNs in identifying newborns with late-onset sepsis, with a sensitivity of 87.5 %, a specificity of 100 % and an AUC of 0.95." (PMID 27116911, 2016). "Various biological markers such as PCT, CRP, interleukins, and myeloid cells expressing triggering receptor-1 (TREM-1) have been reported as biomarkers in diagnosis with sepsis." (PMID 26642970, 2015). "It has been shown that a moderate dose of TREM-1 siRNA improves mice survival during polymicrobial sepsis, whereas high-dose siRNA leads to full silencing of TREM-1, blunting neutrophil respiratory bursts and increasing mortality in mice." (PMID 25347935, 2014). "On the other hand, the previous study indicated that blocking of TREM-1 can protect mice against LPS- or CLP-induced sepsis by mTREM-1/IgGl or LPl7." (PMID 24959004, 2014). "TREM-1 was the first TREM identified and initial studies established TREM-1 as an amplifier of the systemic inflammatory response syndrome and sepsis." (PMID 24842612, 2014). "In sepsis the expression of TREM-1 is initially up-regulated by bacterial or fungal products leading to the production of pro-inflammatory cytokines, mainly of tumor necrosis factor-alpha and of interleukin-8." (PMID 25532536, 2014). "Given the significance of TREM-1 in the inflammatory cascade, its gene expression at sepsis onset has been previously investigated." (PMID 25532536, 2014). "TREM-1 (triggering receptor expressed on myeloid cells), a receptor expressed on neutrophils and monocytes, is upregulated in sepsis and seems to tune the inflammatory response." (PMID 25532536, 2014). "In contrast to polymicrobial sepsis, full TREM-1 silencing has been shown to play a protective role in endotoxemia." (PMID 25347935, 2014). "The objective of this study is to describe the pattern of TREM-1 expression on monocytes both on the surface and on the gene level and to evaluate its impact on the outcome of sepsis." (PMID 25532536, 2014). "At first the number of TREM-1 transcripts, the expression of TREM-1 on monocytes and circulating levels of sTREM-1 of the first day of sampling were measured in relation with the stage of sepsis." (PMID 25532536, 2014). "Trem-1 expression was tendentially higher (p = 0,07) on monocytes and lower on neutrophils of patients with severe sepsis." (PMID 23414215, 2013). "To have an insight into the functional activity of the receptor we correlated Trem-1 expression on neutrophils and monocytes in sepsis patients with the cytokine release after stimulation with LPS and LTA." (PMID 23414215, 2013). "Why do we and others find a differential pattern in sepsis with high soluble Trem-1 and low neutrophil-surface TREM-1?" (PMID 23414215, 2013). "In patients with severe E. coli sepsis we found a trend towards lower Trem-1 on neutrophils but higher soluble Trem-1 (compared to patients with simple sepsis)." (PMID 23414215, 2013). "Since dexamethasone inhibits release of TNFα from whole blood of patients with sepsis, we investigated the role of TNFα on the observed effect of dexamethasone inhibition of TREM-1/sTREM-1 expression." (PMID 24350219, 2013). "It has been shown that in patients with sepsis and in mice with experimental LPS induced septic shock, Trem-1 is upregulated on neutrophils." (PMID 23414215, 2013). "The neutrophil expression of Trem-1 is tendentially lower in patients with severe sepsis (severe sepsis vs. simple sepsis: Trem-1: 19,5 (±7,33) vs 24,00 (±11,91); p > 0,05)." (PMID 23414215, 2013).
Sepsis (continued). "TNF-α, PCT and soluble Trem-1 (sTREM) values were significantly higher (p < 0.05) in patients with severe sepsis compared to simple sepsis." (PMID 23414215, 2013). "Despite the identification of several recent molecules in patients with infection, such as the receptor expressed on myeloid cells-1 (TREM-1), these lack specificity in sepsis pathophysiology." (PMID 22264245, 2012). "Both membrane and soluble TREM-1 are increased in inflammatory pathologies in humans, and inhibition of TREM-1 improves outcome in murine models of sepsis and inflammatory bowel disease." (PMID 21364762, 2011). "The presented data suggest that TREM-1 expression on neutrophils and monocytes is decreased upon transition from sepsis to severe sepsis/shock in a fashion depending on the underlying type of infection and on the causative pathogen." (PMID 22050935, 2011). "MFI of TREM-1 on the membrane of monocytes of patients bearing infections of monomicrobial origin at severe sepsis/shock was greater than of patients with infections of polymicrobial origin at severe sepsis/shock (P = 0.032)." (PMID 22050935, 2011). "Expression of TREM-1 on the membranes of monocytes is decreased in patients with severe sepsis/shock and polymicrobial infections compared to patients with sepsis." (PMID 22050935, 2011). "That was also the case for TREM-1 expression on neutrophils among patients with VAP/HAP (P = 0.049 between severe sepsis/shock and sepsis)." (PMID 22050935, 2011). "Within patients bearing intrabdominal infections, expression of TREM-1 was significantly lower on neutrophils and on monocytes at severe sepsis/shock than at sepsis." (PMID 22050935, 2011). "During the course of sepsis, TREM-1 amplifies infection-induced inflammatory response signals primarily through the mediation of adapter protein DAP12 on the cell surface." (PMID 21356122, 2011). "BACKGROUND: Triggering receptor expressed on myeloid cells-1 (TREM-1) is one of the more recently described biomarkers for sepsis and currently of great interest, as an inhibitor called nangibotide (Inotrem, Paris, France) for TREM-1 has made it into a phase 3 study for the treatment of sepsis." (PMID 42015279, 2026). "Given the absence of FDA-approved TREM-1 inhibitors, recent research has focused on identifying small molecules capable of modulating TREM-1 expression and activity, offering potential breakthroughs in the treatment of sepsis, inflammatory diseases, and immune disorders." (PMID 41226426, 2025). "LP17 is a TREM-1 blocking peptide that has been proven to reduce cytokine secretion in macrophages and improve hemodynamic parameters and survival rates in LPS-induced sepsis mouse models." (PMID 41209006, 2025). "Previously, it was believed that Trem1 primarily played a role in infectious diseases, but recently it has been determined that soluble Trem1 is a mediator of several inflammatory diseases, including colitis, rheumatoid arthritis, psoriasis, and sepsis." (PMID 41300301, 2025). "Neutrophil dysfunction in sepsis includes reduced chemiluminescence intensity, while specific protein activations (e.g., CD88, TREM-1) may serve as diagnostic biomarkers for sepsis." (PMID 40364841, 2025). "TREM-1 has emerged as a critical modulator of the inflammatory response in sepsis." (PMID 41226426, 2025). "Inhibiting TREM-1 signaling has protective effects in a variety of inflammatory conditions, including inflammatory arthritis, inflammatory bowel disease, pancreatitis, sepsis, myocardial inflammation, hemorrhagic shock, and acute ischemia–reperfusion." (PMID 41226426, 2025). "Therapeutic inhibition of TREM-1 has shown promising results in experimental sepsis animal models." (PMID 41226426, 2025). "Furthermore, peritoneal neutrophils from patients with microbial sepsis exhibit increased TREM-1 expression, corroborating its role in sepsis-related immune dysregulation." (PMID 41226426, 2025).